IL6 (interleukin 6)
Diseases named in the same sentence as IL6 in open-access papers (continued):
Sharing a sentence is not in itself a finding about the gene and the disease.
Sepsis (continued). "Interleukin-6 (IL-6) is considered one of the major markers of lethal sepsis, for example as demonstrated in studies using IL-6 knockout mice but is not a target for treatment because in short-term mortality studies anti-IL-6 strategies were unsuccessful." (PMID 19284588, 2009). "Here, we identify novel cooperative actions of STAT3 and GSK3 that control IL-6 production by glia during sepsis-induced neuroinflammation." (PMID 19284588, 2009). "IL-6 causes an increased expression of C5aR in various organs, such as lung, liver, kidney and heart during CLP-induced sepsis." (PMID 19416544, 2009). "Among the milieu of cytokines induced during sepsis, the best correlation of plasma cytokine concentration with mortality rate has been made with IL-6." (PMID 19881187, 2009). "TNFα and IL-6 production from LPS-stimulated monocytes was lower in patients with VAP-related sepsis than with sepsis due to other infections." (PMID 19883512, 2009). "High concentrations of TNF-α are found in BAL fluids from patients with sustained ALI and ARDS, and high levels of IL-6 have been described in a number of acute conditions such as burns, major surgery and sepsis." (PMID 19799777, 2009). "Studies have also shown that circulating concentrations of TNF-α, IL-1β, and IL-6 increase significantly in the early, hyperdynamic stage of sepsis and remain elevated in the late, hypodynamic stage of sepsis." (PMID 18680601, 2008). "As authors stated “CRP, IL-6 and LBP appear to be superior to PCT as diagnostic markers for infection and sepsis in patients." (PMID 19578505, 2008). "Monocytes are potent for the release of pro- and anti-inflammatory mediators within the first 24 hours upon advent of fever related to sepsis; serum stimulates further release of IL-6 within the first 12 hours." (PMID 18385814, 2008). "Logistic regression revealed that among the seven candidate risk factors (admission plasma gelsolin, IL-6, IL-10, TNF-α, albumin, age and sex), admission plasma gelsolin was the only independent factor able to predict the occurrence of severe sepsis." (PMID 18706105, 2008). "In the present study, plasma levels of IL-6 and IL-8 allowed to define a group with short duration of the fever episode and a group with severe infection or even blood culture positive sepsis." (PMID 18321393, 2008). "It is believed that PCT is produced by the liver and other organs (adipocytes, lungs, muscles cells) and peripheral blood mononuclear cells, modulated by lipopolysaccharides and sepsis-related cytokines (Tumor Necrosis Factor α, IL-2, IL-6)." (PMID 19578505, 2008). "The peritonitis-induced sepsis caused a significant fall of arterial pH and markedly increased plasma levels of TNF-α and IL-6." (PMID 19108740, 2008). "Interleukin-6 (IL-6) production is a marker of sepsis-related mortality and poor outcome in models of pneumococcal disease and increased IL-6 production has been shown in the lungs of pneumococcal-infected mice." (PMID 17850649, 2007). "• The route of administration of nutrition (parenteral versus enteral) in sepsis influences circulating levels of IL-6 and IL-10 in rodents." (PMID 17634149, 2007). "Previous studies have suggested that IL-6 serves as both a marker and a mediator for the severity of sepsis." (PMID 17505683, 2007). "Other studies have shown that active site-inhibited F VIIa (F VIIai) and TFPI reduce the expression of pro-inflammatory cytokines IL-6 and IL-8 in vivo, decrease coagulation and thereby prevent death in a lethal baboon model of Escherichia coli-induced sepsis." (PMID 17660410, 2007). "Cytokines like interleukin (IL)-1, IL-6, and tumour necrosis factor-alpha have been studied in animal models and in clinical sepsis cohorts." (PMID 17346334, 2007). "To evaluate the significance of IL-6 and KC in predicting outcome of lethal sepsis, we compared their circulating levels in dying (in a moribund state) versus non-dying (in a non-moribund state) septic mice at 52 h post CLP." (PMID 17987129, 2007).
Sepsis (continued). "PN also resulted in significantly lower IGFBP-I levels compared with EN in septic animals, despite the greater recovery of IL-6 and IL-10 in PN-fed animals with sepsis." (PMID 17634149, 2007). "We studied the ability of procalcitonin, lipopolysaccharide-binding protein, IL-6 and C-reactive protein to identify patients with infection and sepsis." (PMID 16569262, 2006). "Using a cut off level of 25 pg/ml, IL-6 had a sensitivity of 81.1% and a specificity of 78.9% in diagnosing sepsis/severe sepsis." (PMID 16569262, 2006). "The purpose of this study was to determine if there is a relationship between the IL-10 -1082 G/A, IL-6 -174 G/C and CD14 -260 C/T SNPs and risk for or outcome from sepsis in mechanically ventilated very low birth weight (VLBW) infants." (PMID 16611358, 2006). "Only IL-6 reached a sensitivity and specificity of approximately 80% in diagnosing sepsis with a cut-off level of 25 pg/ml." (PMID 16569262, 2006). "The generation of pro-inflammatory cytokines during sepsis, including IL-1, IL-6, and IL-8 as well as TNF-alpha activates the endothelial lining cells." (PMID 17062126, 2006). "• In a cohort of patients with less severe community-acquired infections, CRP, IL-6 and LBP appear to be superior to PCT as diagnostic markers for sepsis." (PMID 16569262, 2006). "IL-6, lipopolysaccharide-binding protein and C-reactive protein performed best in distinguishing between systemic inflammatory response syndrome and sepsis, with an area under the curve larger than 0.84 (P < 0.01)." (PMID 16569262, 2006). "A correlation between IL-6 levels and the severity/mortality of sepsis has been observed in several studies." (PMID 16569262, 2006). "This is contrary to our data, which suggest that IL-6 is superior to PCT as a diagnostic marker for infection and sepsis." (PMID 16569262, 2006). "Clinical and experimental studies have shown a significant elevation in IL-6 production after burn injury and sepsis, which correlates with suppressed cell-mediated immunity and increased mortality." (PMID 16168063, 2005). "Sirt4 KO mice exhibited higher levels of serum AST/ALT, more severe liver tissue structure damage, and higher serum concentrations of proinflammatory factor IL‐6 after CLP surgery, which demonstrates that endogenous Sirt4 is an important molecular barrier against liver injury caused by sepsis." (PMID 41523985, 2026). "Furthermore, the sepsis group exhibited significantly elevated levels of IL-6, CRP, PCT, and SOFA scores (P<0.05), lower lymphocyte counts (P = 0.017), and more pronounced coagulation abnormalities, hypoalbuminemia, and increased cardiac/renal markers." (PMID 41988187, 2026). "The G–C polymorphism at position 174 of the IL6 gene (rs1800795) influences negative outcomes in several inflammatory diseases, including sepsis." (PMID 41598258, 2026). "Although muscle‐derived IL‐6 is classified as a myokine with systemic endocrine effects, its plasma concentrations are often elevated in critically ill individuals particularly during the acute phase of sepsis." (PMID 41573125, 2026). "Additionally, DYY inhibited inflammation (TNF-α, IL-1β, and IL-6), cell apoptosis, and promoted proliferation in sepsis, as well as the promotion of tight junction proteins (claudin-1, occludin, and ZO-1)." (PMID 41948377, 2026). "Furthermore, serum lactate levels in sepsis patients were positively correlated with levels of the pro‐inflammatory cytokine IL‐6, thus indicating a link between lactate and the severity of inflammation in sepsis." (PMID 41532698, 2026). "Additionally, sepsis patients with CG/GG genotypes expressed significantly increased levels of IL-1β, IL-6, and ICAM-1 than those with CC genotype." (PMID 42311758, 2026).
Sepsis (continued). "The target receptor C3aR is shown to be significantly upregulated in human peripheral blood mononuclear cells during sepsis and is considered to be a key mediator in the early production of proinflammatory mediators such as IL-6 or TNFa and the severity of disease outcome during endotoxemic sepsis." (PMID 40253667, 2025). "Although IL-6 is a general indicator of sepsis severity, its specific role as an SAE biomarker remains unclear." (PMID 40635709, 2025). "Emerging evidence positions IL-6 as a robust biomarker for sepsis severity and prognosis." (PMID 41256846, 2025). "Similarly, GYY-4137 significantly reduced the serum levels of TNFα and interleukin-6 (IL-6), as well as iNOS expression, in mice with sepsis." (PMID 40559470, 2025). "As expected, IL-6 levels rose in sepsis and increased further when neutropenia was present." (PMID 41155261, 2025). "Indeed, the higher serum creatinine, alanine transaminase, and cytokines (TNF-α and IL-6) with the lower SCFAs (propionate, acetate, and butyrate) in patients with sepsis compared with the healthy control was demonstrated." (PMID 41444762, 2025). "For instance, in 97 patients with sepsis, CytoSorb therapy was shown to capture interleukin (IL)-6, reflected by a gradient across the cartridge, but this did not result in lower plasma IL-6 concentrations compared to a control group receiving standard of care." (PMID 40117010, 2025). "As the circulating level of IL-6 correlates highly with the outcome of patients with sepsis, identifying the supply source of IL-6 and elucidating its mechanism may improve our understanding and treatment of sepsis." (PMID 39568061, 2025). "In this review, we aim to summarize existing knowledge on the role of UC IL-6 as a predictor of neonatal outcomes, including sepsis, respiratory morbidity and neurodevelopmental prognosis, while also highlighting the challenges and future perspectives for its clinical application." (PMID 41302151, 2025). "Local inflammation and sepsis are primarily mediated by IL-6 and TNF-α." (PMID 39999222, 2025). "The serum profile of the IL-6 in sepsis was monitored at narrow intervals over 24 h." (PMID 39955435, 2025). "Our review focused on CS, IL-6 related signaling pathways, and sepsis-related chronic diseases." (PMID 39891057, 2025). "Additionally, procalcitonin (PCT) and interleukin-6 (IL-6) are also commonly utilized biomarkers in sepsis." (PMID 40568199, 2025). "The decrease of IL-6 after sepsis treatment may be an indicator of better prognosis and survival of patients with sepsis." (PMID 40281760, 2025). "Higher blood IL-6 levels upon ICU admission were significantly associated with an increased risk of death in non-elderly patients with sepsis." (PMID 39800741, 2025). "Similarly, while M1mAChR-mediated orexinergic enhancement reduced serum levels of TNFa and IL-1b, elevated levels of other cytokines believed to play a key role in sepsis pathobiology (eg, IL-6) respond to orexin via a mechanism that is M1mAChR independent." (PMID 40909798, 2025). "Furthermore, the biosensor exhibits improved stability and enhancedselectivity against other sepsis-related antigens, positioning it as a highly promisingtool for IL-6 detection in POC diagnostics." (PMID 40704602, 2025). "Therefore, this systematic review and meta-analysis aims to comprehensively evaluate the available evidence, and to answer pivotal questions regarding the prognostic significance of IL-6 in sepsis." (PMID 40149943, 2025). "Filgrastim upregulates IL-6 and IL-8 levels in febrile neutropenia (Araújo 2017), but this pharmacodynamic effect does not compromise their diagnostic utility for sepsis." (PMID 40647525, 2025). "Procalcitonin, C-reactive protein (CRP), CD14, and interleukin-6 can qualify as general sepsis biomarkers by broad applicability across all sepsis subtypes, consistently reported across adult, pediatric, and neonatal cohorts, reflecting a conserved pathophysiological role." (PMID 40478618, 2025).
Sepsis (continued). "Our study examines the time-dependent changes in IL-6 in sepsis at small intervals." (PMID 39955435, 2025). "High levels of Il6 have been linked to the development of sepsis and are connected to negative results because of its inflammatory properties and capacity to trigger a cytokine storm." (PMID 40792069, 2025). "Notably, pre-administration of IL6 and dexamethasone maximally stimulated the acute phase response and mitigated sepsis." (PMID 40061452, 2025). "Persistently elevated or rising IL-6 levels may serve as a biomarker to identify candidates for such immunomodulatory therapies, advancing a precision medicine approach to sepsis." (PMID 40959673, 2025). "The high IL-6 clearance, a pro-inflammatory cytokine, might be an interesting adjunctive therapeutic approach for patients with sepsis." (PMID 39810111, 2025). "A study using Wistar rats likewise showed that IL-6 levels rise during sepsis and suggested that this could serve as an early marker of the condition." (PMID 41517447, 2025). "IL-6, as a pro-inflammatory cytokine, typically shows significantly elevated levels in sepsis; however, due to its elevation in various inflammatory states, its specificity may not be as robust as that of HBP." (PMID 40568199, 2025). "However, in murine models of sepsis induced by LPS, it is characterized by an excessive synthesis of inflammatory cytokines, such as IL-6, IL-12 and IFN-γ, endothelial damage and coagulation disorders." (PMID 41156807, 2025). "PCT combined with IL-6 gave better accuracy for term infants with sepsis." (PMID 40892314, 2025). "This study aimed to investigate the effects of cetirizine and dexamethasone (alone and in combination) on serum levels of Maresin-1 (MaR-1), TNF-α, IFN-γ, IL-1, IL-2, IL-6, IL-8, and IL-10 in a rat model of sepsis induced by the cecal ligation and puncture (CLP) method." (PMID 41517447, 2025). "Further, IMHA in dogs has a similar cytokine profile to sepsis, while SRMA is associated with a systemic inflammatory response and the overproduction of cytokines interleukin (IL)‐6, IL‐17, transforming growth factor (TGF)‐β, vascular endothelial growth factor (VEGF) and CC‐motif ligand 19 (CCL19)." (PMID 40485041, 2025). "Similarly, human studies on sepsis patients have shown a time-dependent reduction in plasma levels of IL-1β, IL-6, IL-8, and TNF in those receiving treatment with the β2 microglobulin adsorption column." (PMID 40234407, 2025). "Interleukin-6 (IL-6) is an early biomarker for sepsis and necrotizing enterocolitis (NEC)." (PMID 39958363, 2025). "Understanding these differences may enhance the accurate use of IL-6 as a biomarker, which can contribute to improving the clinical practice in sepsis." (PMID 39800741, 2025). "Vitamin C supplementation in sepsis patients led to significant improvements over 12 months, with reductions in IL-6 (345.16 ± 128.52 to 245.12 ± 83.78 pg/mL), C-reactive protein (CRP) (175.31 ± 62.43 to 114.57 ± 38.67 mg/L), and malondialdehyde (MDA) levels (8.94 ± 3.21 to 5.79 ± 2.18 nmol/mL)." (PMID 40296930, 2025). "For example, in CLP-induced sepsis, an IL-6 value of greater than 3 ng/mL combined with a GC value of less than 200 ng/mL may indicate iGC insufficiency." (PMID 40048257, 2025). "The pro-inflammatory cytokines, TNF-α and IL-6, play a crucial role in the initial phase of sepsis." (PMID 40885907, 2025). "Notably, Siv@NMs treatment achieved significantly greater reductions in MPO-DNA, H3cit, TNFα, and IL-6 levels, further validating the enhanced therapeutic efficacy of the nanoparticle formulation in suppressing systemic NETosis and inflammation during sepsis." (PMID 40574078, 2025). "Sepsis presence and older age influenced the level of IL-6 (age p=0.035; sepsis presence p>0.0001)." (PMID 39935482, 2025). "Notably, pro-DCD-specific IgGs (“A-IgGs”) significantly elevated sepsis-induced systemic accumulation of G-CSF, IL-6 and MCP-1, three surrogate markers of experimental and clinical sepsis." (PMID 40534887, 2025).
Sepsis (continued). "Notably, HMGB1 levels were found to increase after IL-6 levels in sepsis, and anti-HMGB1 antibody have been shown to reduce mortality, suggesting HMGB1 as a potential therapeutic target." (PMID 39849347, 2025). "Combined with established biomarkers like lactate and IL-6, a multi-biomarker approach could enhance sepsis management by distinguishing between active inflammation and immune exhaustion." (PMID 40094854, 2025). "As liver failure is a critical determinant of sepsis progression, our findings suggest that IL-6 overexpression may serve as an early indicator of hepatic stress in sepsis." (PMID 40178612, 2025). "Furthermore, studies showed that blocking IL-6 trans-signaling reduces macrophage numbers in a mouse model of sepsis and that IL-6 trans-signaling plays a crucial role in MCP-1 upregulation in immune-mediated myopathy." (PMID 40368371, 2025). "Indeed, IL-6 levels were highest in neutropenic patients with concomitant sepsis, far exceeding levels observed in patients with either neutropenia or sepsis alone." (PMID 41155261, 2025). "Furthermore, dedicated studies are needed to investigate the prognostic value of IL-6 in specific sepsis subpopulations, such as immunosuppressed patients, pediatric patients, and those with different infection sources or pathogens." (PMID 40149943, 2025). "By synthesizing data from original articles reporting serial IL-6 measurements in sepsis, this meta-analysis aims to provide a definitive assessment of IL-6’s role as a prognostic biomarker and its potential to guide clinical decision-making in the management of this life-threatening condition." (PMID 40149943, 2025). "NF‐κB activation results in the production and release of various pro‐inflammatory cytokines, such as tumor necrosis factor‐alpha (TNF‐α), interleukin‐1 alpha (IL‐1α), IL‐6, and IL‐8, which contribute to the cytokine storm and systemic inflammation during sepsis." (PMID 40599085, 2025). "Our hypothesis was experimentally tested by administering TCZ treatments at various time points in rats with lipopolysaccharide (LPS)-induced sepsis, using IL-6 as a biomarker." (PMID 39955435, 2025). "Finally, experimental data showed that the concentration of interleukin-1β (IL-1β), tumor-necrosis-factor-alpha (TNF-α), and interleukin-6 (IL-6) increased significantly, thereby accelerating inflammatory response and exacerbating sepsis-induced AKI." (PMID 40083322, 2025). "IL-6 levels in serum typically range from 1 to 25 pg/mL, but can exceed 1 ng/mL in sepsis." (PMID 39910395, 2025). "So, take effective management to blocked over-activation of IL-6 related signaling pathways in these chronic diseases may be seen as the better method for prevention and treatment for sepsis." (PMID 39891057, 2025). "This article summarized the inflammatory mechanisms of IL-6 cross-talked with other mediators of some chronic diseases in vitro, animal models, and human experiments, leading to the activation of pathways and accelerating the progression of sepsis." (PMID 39891057, 2025). "Moreover, when combined with PCT, IL-6 has been shown to correlate with the severity and prognosis of sepsis, indicating its usefulness in tracking disease progression." (PMID 41011807, 2025). "Therefore, it is important to study the relationship between IL-6 and its related pathways in sepsis-related chronic diseases." (PMID 39891057, 2025). "Similarly, in 57 patients meeting SIRS/sepsis criteria, IL-6 peaked on day 1 (mean 153 ± 33 pg/mL) and correlated with APACHE II scores, establishing IL-6 as an early biomarker of organ dysfunction independent of peritoneal insult type." (PMID 41227298, 2025). "Therefore, IL-6 levels should be interpreted with caution when predicting mortality in elderly patients with sepsis." (PMID 39800741, 2025). "Nevertheless, its established significance in assessing sepsis outcomes indicates that monitoring IL-6 levels may offer insights into the prognosis of patients with SAE." (PMID 40635709, 2025).